HIF1A (hypoxia inducible factor 1 subunit alpha)
Diseases named in the same sentence as HIF1A in open-access papers (continued):
Sharing a sentence is not in itself a finding about the gene and the disease.
triple-negative breast carcinoma (continued). "Hyperactivation of HIF-1α is crucial in progression of triple-negative breast cancer, but how HIF-1α stability is maintained in a hypoxia-independent manner is unclear." (PMID 30367042, 2018). "Next, we analysed and compared CSRP2 and HIF-1α protein expression in 48 triple negative breast cancer tissue array samples, and the results were scored by a pathologist." (PMID 29976963, 2018). "We aimed to better understand the mechanism underlying HICR in a triple negative breast cancer cell line, MDA-MB-231, with a focus on the role of HIF-1α." (PMID 29036915, 2017). "In this study, we aimed to understand the mechanism underlying HICR in triple negative breast cancer (TNBC), since TNBC tumors are known to frequently carry a hypoxic phenotype and HIF-1α is known to be frequently over-expressed in these tumors." (PMID 29036915, 2017). "XBP1 interacts with hypoxia-inducible factor 1-alpha (HIF1α) in triple negative breast cancer and drives tumor progression by inducing hypoxia signature gene expression." (PMID 27303918, 2016). "Additionally, liposome-encapsulated echinomycin, a HIF-1α inhibitor, has been shown to eliminate established metastases in triple-negative breast cancer." (PMID 40552073, 2025). "Furthermore, in triple-negative breast cancer cells, both HIF-1α and HIF-2α can bind to the promoter region of CD73 and other genes encoding immunosuppressive molecules, such as PD-L1." (PMID 40746883, 2025). "However, multiple studies have also shown that CPNE1 promotes aerobic glycolysis and metastasis in triple-negative breast cancer (TNBC) through the PI3K/AKT/HIF-1α signaling pathway, thereby accelerating tumor progression." (PMID 39351539, 2024). "Notably, it has been reported that XBP1s controls the hypoxia-inducible factor-1α (HIF1α) transcriptional program in triple-negative breast cancer where XBP1s functions upstream of HIF1α26." (PMID 34493732, 2021). "Rescue of HIF-1α expression restores MCU-silenced triple-negative breast cancer cell motility." (PMID 32152662, 2020). "Nonetheless, XBP1 promotes the progression of triple-negative breast cancer (TNBC) through synergy with hypoxia inducible factor-1 alpha (HIF1α) to support tumor-initiating cell function and the metastatic ability of cancer cells under adverse environmental conditions." (PMID 33267910, 2020). "The aims of this study were to explore the expression of hypoxia inducible factor-1α (HIF-1α) and c-myc protein in triple-negative breast cancer (TNBC) and its clinical prognostic significance, and to establish a prediction model for postoperative survival of TNBC based on nomogram." (PMID 31577739, 2019). "To explore whether MALAT1 regulates proliferation and invasion abilities of triple-negative breast cancer cells through XBP1-HIF1α, we firstly detected the expressions of XBP1 and HIF1α in MDA-MB-231 by qRT-PCR after the knockdown of MALAT1." (PMID 29416769, 2018). "Finally, amongst the highlighted genes was Ebf1 transcription factor and oncogene that is shown to assemble a transcriptional complex with Hif1a to suppress p300 activity in triple negative breast cancer and is included in the neural crest gene regulatory network." (PMID 41446274, 2025). "In addition, it has been found that ZHX2 may promote HIF1α oncogenic signaling in triple-negative breast cancer (TNBC) and hypoxia-induced phase separation of ZHX2 may alter chromatin looping to promote metastasis." (PMID 41480542, 2025). "Importantly, the shared high expression of HIF1α and its target genes in triple-negative breast cancers underscores the importance of our findings and the opportunities afforded by the models we describe here for the future pursuit of additional mechanistic and translational investigations." (PMID 34294889, 2022). "Using androgen-independent prostate cancer (DU145) and triple-negative breast cancer (KPL-4) cell lines, we demonstrated constitutive activation and reciprocal regulation of STAT3, PKM2, and HIF-1α." (PMID 41828578, 2026).
triple-negative breast carcinoma (continued). "The HIF-1α/miR-142-3p/LOX/ITGA5 pathway has been studied in the context of chemotherapy resistance, particularly in triple-negative breast cancers." (PMID 39857068, 2025). "A high level of HIF-1α at diagnosis signifies early relapse and metastasis, and increased expression of HIF-1 targeted genes are found in the triple-negative breast cancer subgroup." (PMID 36674719, 2023). "Recent studies showed that HIF-1α was a co-regulator of XBP1 and induced its expression in triple negative breast cancer." (PMID 37752569, 2023). "In triple-negative breast cancer (TNBC), highly-expressed LINK-A actives BRK kinase to phosphorylate HIF-1α and prevent hydroxylation for enhancing p300-HIF-1α association and the resulting HIF-1α transcriptional activity." (PMID 36918934, 2023). "The clue of the study was to inspect the results of silencing HIF-1α, HIF-2α, or both isoforms in triple-negative breast cancer cell line MDA-MB-231 xenografts." (PMID 36139678, 2022). "Here, the authors show that hypoxia induces T and NK cell dysfunction through HIF1α-mediated epigenetic suppression of effector gene expression, conferring resistance to anti-PD1 blockade in triple negative breast cancer models." (PMID 35840558, 2022). "Mitochondrial Ca2+ uptake is necessary for the progression of triple-negative breast cancer (TNBC) in vivo and it can also activate the hypoxia-inducible factor-1 alpha (HIF-1α) signal pathway, which contributes to tumor growth and metastasis." (PMID 35743109, 2022). "In triple-negative breast cancer, MIR210HG potentiated the metabolic transcription factor HIF-1α translation via directly binding to the 5’-UTR of HIF-1α mRNA, leading to increased HIF-1a protein level." (PMID 34900667, 2021). "The expression of HIF-1α, MMP-2, VE-cadherin, and Twist-1 in triple-negative breast cancer cells is higher than that in non-triple-negative breast cancer cells." (PMID 33363175, 2020). "Cardamonin inhibited growth of the triple negative breast cancer cell line MDA-MB-231 in vitro and in vivo by suppressing HIF-1α mediated cell metabolism." (PMID 31455352, 2019). "This agrees with a previous report where the poor prognosis of triple-negative breast cancers correlated with the assembly of a transcriptional complex of XBP1 and HIF1α." (PMID 28674530, 2017). "Enforced expression of lncRNA-LET leads to reduced HIF1-α and results in lower metastatic potential, while LINK-A interacts with tyrosine protein kinase 6 to promote stabilization of HIF1-α in triple negative breast cancer." (PMID 28747406, 2017). "Furthermore, HIF1α induces simultaneous increased expression of CD73, CD47, and PD-L1 in triple-negative breast cancer." (PMID 40746883, 2025). "We demonstrated that STAMBPL1 increased HIF1A transcription in a non-enzymatic manner, thereby activating the HIF1α/VEGFA signaling pathway to facilitate triple-negative breast cancer angiogenesis." (PMID 40208233, 2025). "Moreover, chrysin, a natural compound that has HIF1α and VEGF inhibiting capacity was also reported to act as a radiosensitizer in triple-negative breast cancer cell lines." (PMID 37460927, 2023). "In particular, HIF-1α is highly expressed in triple-negative breast cancer, which is hard to treat due to the lack of a therapeutic target." (PMID 36296726, 2022). "In this study, we demonstrated that the pregnane alkaloid 1 could downregulate HIF-1α and block the VEGF/VEGFR2 axis and its downstream signaling pathways in triple-negative breast cancer cells." (PMID 36296726, 2022). "Similarly, in triple-negative breast cancer, increased activity of the HIF1 pathway was detected, and collagen prolyl 4-hydroxylase 1 (P4HA1) was demonstrated to enhance HIF1α stability by modulating α-ketoglutarate and succinate levels." (PMID 36551845, 2022). "Two reports in triple-negative breast cancer found that β-escin did not regulate hypoxia-induced HIF1α." (PMID 34439084, 2021).
triple-negative breast carcinoma (continued). "In triple-negative breast cancer, long intergenic non-coding RNA for kinase activation (LINK-A) mediates hypoxia inducible factor 1 subunit alpha (HIF1α) phosphorylation and stabilization by protein tyrosine kinase 6 (BRK) and leucine rich repeat kinase 2 (LRRK2) interaction." (PMID 32429086, 2020). "Work in triple negative breast cancer (TNBC) cells points to an interaction between XBP1 and hypoxia-inducing factor 1α (HIF1α) that form a transcriptional complex to promote efficient transcription of HIF1α target genes." (PMID 31071975, 2019). "DNA methylation status at CpG and non-CpGs in the HIF-1α promoter were tested in eight cases of diagnosed human luminal subtype and three cases of diagnosed triple negative breast cancer samples." (PMID 30940798, 2019). "Therefore, in this study, we chose RT-R-MDA-MB-231 cells derived from MDA-MB-231 cells, from triple negative breast cancers (TNBCs), and evaluated whether RT-R-MDA-MB-231 cells increased the levels of HIF-1α and LOX." (PMID 33126606, 2020). "However, ORAI3 silencing suggested that ORAI3 is not a regulator of HIF1α after hypoxic exposure in MDA-MB-468 Basal-A triple negative breast cancer cells." (PMID 30754719, 2019). "Therapeutic strategies that include drugs that inhibit HIF-1α protein accumulation or perhaps TAZ target gene products may improve outcome in women with triple negative breast cancer, who are currently treated with cytotoxic chemotherapy with durable response rates of less than 20%." (PMID 26059435, 2015). "In addition to the previous report that integrin α6β1-activated FAK induces GLI-1 expression in triple-negative breast cancer, our present results with ITGA11 KD demonstrated that integrin α11 induced activation (nuclear translocation) of GLI-1, but not HIF1α and EZH2." (PMID 38664825, 2024).
clear cell renal cell carcinoma (90 papers, 2009 to 2026). "Clear-cell renal cell carcinoma (ccRCC) is associated with the mutated von Hippel–Lindau (VHL) gene leading to the activation of hypoxia-inducible factor 1A (HIF1A) and subsequent overexpression of erythropoietin (EPO)." (PMID 40332447, 2025). "In clear cell renal cell carcinoma (ccRCC), where HIF-1α/VEGF-α signaling driven by VHL inactivation is a hallmark, the biological effects of zinc are not fully understood." (PMID 41220925, 2025). "In clear cell renal cell carcinoma (ccRCC), both HIF-1α and HIF-2α are stabilized by VHL loss, leading to the decrease in ferroptosis sensitivity to erastin or BSO via fatty acid β-oxidation and mitochondrial ATP-synthesis." (PMID 37048123, 2023). "In hypoxic conditions, Ceruloplasmin (CP) induces generates oxygen radicals, while inducing activation of HIF-1α, Overexpression of CP in clear cell renal carcinoma is linked to oncogenic pathways and worse survival rates." (PMID 35924146, 2022). "Previous studies showed that HIF1α was activated in renal clear cell carcinoma and associated with a more aggressive phenotype." (PMID 35036081, 2022). "HIF-2α is present in tumor cells (such as those in clear-cell renal cell carcinoma associated with von Hippel-Lindau disease), and HIF-1α has been found in normal cells of the human body." (PMID 35203690, 2022). "Loss of function mutations of VHL protein, a key ECV component in renal clear cell carcinoma (RCC) results in elevated HIF1α levels." (PMID 33603169, 2021). "Mutation or promoter hypermethylation of VHL in clear-cell renal carcinoma would give rise to the upregulation of HIF-1α." (PMID 30081604, 2018). "A subset of clear cell renal cell carcinoma (ccRCC) tumors exhibit a HIF1A gene mutation, yielding two ccRCC tumor types, H1H2 type expressing both HIF1α and HIF2α, and H2 type expressing HIF2α, but not functional HIF1α protein." (PMID 28092369, 2017). "VHL is an established tumor suppressor that is frequently mutated in clear cell renal carcinoma (ccRCC) and functions by facilitating the degradation of HIF1α and pAkt." (PMID 29053101, 2017). "Reduced pVHL trafficking was recently demonstrated in clear cell renal cell carcinoma, and was associated with strong nuclear localization of HIF-1α and shorter patient survival." (PMID 19347037, 2009). "For instance, glutamine-addicted clear cell renal carcinoma cells deplete extracellular glutamine, activating HIF-1α and inducing IL-23 secretion by tumor-associated macrophages, which amplifies regulatory T cell activity and suppresses effector T cell function." (PMID 41323791, 2025). "For example, HIF-1α was reported to remain relatively high even in a richly vascularized (oxygen rich) microenvironment in clear cell renal cell carcinoma (ccRCC, sporadic ccRCC cases are often caused by aberrations in the VHL (encode von Hippel–Lindau tumor suppressor protein) gene)." (PMID 39757165, 2025). "Interestingly, the expression of components of TGF-β signaling and HIF-1α were associated with a poor prognosis of patients with clear cell renal cell carcinoma." (PMID 37937056, 2023). "Moreover, the Warburg effect-like glucose metabolism was reported in a HIF-1α-deficient clear cell renal cell carcinoma cell line." (PMID 30634433, 2019). "The most well-known and privileged ubiquitination-related enzyme of HIF-1α is pVHL E3 ubiquitin ligase, whose loss or inactivation can lead to the formation of tumors in multiple organs, such as hemangioblastomas of the brain, renal cysts and clear cell renal cell carcinoma, etc.." (PMID 39757165, 2025). "In clear-cell renal cell carcinoma models, stabilization of HIF-1α by CoCl2 led to increased MUC1 mRNA levels, whereas HIF-1α knockdown via small interfering RNA and the HIF-1 inhibitor YC-1 reduced hypoxia-induced MUC1 expression." (PMID 41416421, 2026). "HIF-1α can cause the expression of its antisense RNA, HIF1A-AS2, in clear cell renal cell carcinoma." (PMID 41614928, 2026).
clear cell renal cell carcinoma (continued). "In renal clear cell carcinoma, Trim21 acts as an E3 ubiquitin ligase for HIF-1α, promoting its ubiquitination and degradation, thereby inhibiting glycolysis and suppressing the growth and metastasis of renal clear cell carcinoma." (PMID 41298345, 2025). "Clear cell renal cell carcinoma (ccRCC) is marked by aberrant hypoxia-driven signaling and enhanced angiogenesis mediated by hypoxia-inducible factor 1-alpha (HIF-1α) and vascular endothelial growth factor alpha (VEGF-α)." (PMID 41220925, 2025). "For instance, in clear cell renal cell carcinoma, it stimulates the translation of Snail Family Transcriptional Repressor 1, and in sarcoma cells, it enhances the translation of Hypoxia Inducible Factor 1 Subunit Alpha (HIF1α)." (PMID 38255791, 2024). "This study delves into the roles of RUVBL1 and HIF1A in the development of clear-cell renal cell carcinoma (ccRCC) and investigates their clinical relevance as prognostic biomarkers." (PMID 38610951, 2024). "Regarding tumor size, previous studies showed a correlation between HIF-1α expression and renal tumor size, particularly in clear cell renal cell carcinoma (ccRCC)." (PMID 38053655, 2023). "It has reported that HIF-1α drives lipid deposition in clear cell renal cell carcinoma by repressing CPT1α, subsequently reducing fatty acid transport into the mitochondria and forcing fatty acids to be stored as lipid droplets." (PMID 36750818, 2023). "The pseudo-hypoxic metabolism of clear cell renal cancer is based on a loss of VHL function, which induces stabilization and upregulation of hypoxia-associated gene products like HIF1A and VEGF." (PMID 35646693, 2022). "A previous study has reported that the expression of PGC-1α is suppressed in clear cell renal cell carcinoma in an HIF-1α-dependent manner." (PMID 35896535, 2022). "LncRNA SNHG6 promotes carcinogenesis by enhancing the translation of YBX1-mediated HIF1α in clear cell renal cell carcinoma." (PMID 35692750, 2022). "Clear cell renal cell carcinomas (ccRCC) highly express carbonic anhydrase IX, targeted by girentuximab due to the overexpression of hypoxia-inducible factor-1 alpha (HIF-1α) as these tumours are fast growing and highly hypoxic." (PMID 34633509, 2021). "The results reinforce our conclusion regarding the ability of Smurf2 to degrade HIF-1α and suggests a potential protective role of Smurf2 in clear cell renal cell carcinoma." (PMID 34611473, 2021). "Accumulating literature has suggested that hZIP1 and HIF-1α play vital roles in the tumor process of clear cell renal cell carcinoma (ccRCC)." (PMID 34926261, 2021). "HIF1A was among the higher expressed genes both in normal kidney and clear cell renal cancer (TCGA)." (PMID 33077781, 2020). "Backgrounds: A number of genetic and biological phenomena imply that tumorigenesis of clear cell renal cell carcinoma (ccRCC) is highly correlated with hypoxia-induced factor-1a (HIF-1α)." (PMID 32047543, 2020). "Mutational inactivation of VHL is the earliest genetic event in the majority of clear cell renal cell carcinomas (ccRCC), leading to accumulation of the HIF-1α and HIF-2α transcription factors." (PMID 32807776, 2020). "In human clear cell renal cell carcinoma, it has been shown that the expression of E-cadherin and HIF-1α was mutually exclusive due to HIF-1α-mediated induction of TCF3, ZFHX1A, and ZFHX1B, which repress E-cadherin gene transcription." (PMID 32733884, 2020). "HIF-2α is a major oncogenic driver in clear cell renal carcinoma (ccRCC) where HIF-1α acts as tumor suppressor." (PMID 32733884, 2020). "Genetic inactivation of VHL leads to stabilization of HIF-1α/HIF-2α and is associated with clear cell renal cell carcinoma (ccRCC) initiation and progression." (PMID 32807776, 2020).